GSDMB (gasdermin B)
Diseases named in the same sentence as GSDMB in open-access papers (continued):
Sharing a sentence is not in itself a finding about the gene and the disease.
bronchiolitis (1 paper, 2024). Inflammation of the bronchioles characterized by swelling of the bronchioles and mucus accumulation. "We identified bronchiolitis-associated loci in gasdermin B (GSDMB) and cadherin-related family member 3 (CDHR3) by genome-wide association study." (PMID 39299705, 2024). "Our results suggest that genetic variants in CDHR3 and GSDMB modulate susceptibility to bronchiolitis, especially when caused by viruses other than RSV." (PMID 39299705, 2024). "We conducted colocalization analysis to assess if the bronchiolitis association in the CDHR3 or GSDMB locus could be mediated by gene expression." (PMID 39299705, 2024). "We used eQTL data from other relevant tissues and more specific immune cell types to assess if the bronchiolitis association in the GSDMB locus could be modulated by genotype-specific gene expression." (PMID 39299705, 2024). "We detected 2 loci, CDHR3 and GSDMB, that were associated with severe bronchiolitis in the GWAS." (PMID 39299705, 2024). "In summary, the current study provides evidence of genetic associations and perhaps genetically mediated functional mechanisms for the CDHR3 and GSDMB loci in severe bronchiolitis." (PMID 39299705, 2024). "The GWAS of bronchiolitis by any causative virus found 2 associated loci (P < 5 × 10−8), located within CDHR3 and GSDMB." (PMID 39299705, 2024). "We showed that regulatory variants in the GSDMB locus may influence GSDMB and ORMDL3 expression in distinct immune cell types and that the genotype-dependent gene expression could mediate susceptibility to severe bronchiolitis." (PMID 39299705, 2024).
Cognitive impairment (1 paper, 2023). Abnormal cognition is characterized by deficits in thinking, reasoning, or remembering. "The role of GSDMD and GSDME-mediated pyroptosis in cognitive impairment have been elucidated, but the mechanisms of other gasdermin family members such as GSDMA, GSDMB, GSDMC and DFNB59 in cognitive impairment remained unclear." (PMID 37332874, 2023).
colorectal tumors (1 paper, 2025). "We found that the transcriptional levels of GSDMA, GSDMC, and PJVK were significantly increased in human colorectal tumors; while, the expression of GSDMB, GSDMD, and GSDME remained unchanged." (PMID 40213993, 2025).
encephalitis (1 paper, 2025). An acute inflammatory process affecting the brain parenchyma. "Mpox virus infection of astrocytes which can lead to neurological complications such as encephalitis, causes pyroptotic cell death via Gasdermin B cleavage." (PMID 40331993, 2025).
epithelial ovarian cancer (1 paper, 2022). "Additionally, various histological subtypes of epithelial ovarian cancer express GSDMB and GSDME differently." (PMID 35198448, 2022).
esophageal adenocarcinoma (1 paper, 2022). A malignant tumor with glandular differentiation arising predominantly from Barrett mucosa in the lower third of the esophagus. "Esophageal adenocarcinoma had the highest frequency of GSDMA (20.69%) and GSDMB (21.84%) amplification." (PMID 35164740, 2022).
glioblastoma (1 paper, 2022). The most malignant astrocytic tumor (WHO grade IV). "Conversely, higher expression levels of GSDMB, GZMA, and GZMB were detected in T cells, whereas NLR4 and CASP5 showed specifically high expression levels in TAMs, and CASP5, GZMA, GZMB, and NLRC4 were barely detected in glioblastoma cells." (PMID 35990696, 2022).
kidney carcinomas (1 paper, 2022). Primary or metastatic malignant neoplasm involving the kidney. "Importantly, we found that the expressions of GSDMB, GSDMC, and GSDMD were higher in kidney carcinomas, and specifically kidney renal clear cell carcinoma (KIRC); which adversely impacted the patient outcome." (PMID 36003332, 2022).
lymph node metastasis (1 paper, 2024). "Conversely, our data showed that membranous GSDMB expression was somewhat correlated with lesser lymph node metastasis." (PMID 38711020, 2024). "A positive nuclear GSDMB expression indicated a lower histological grade and a lower likelihood of lymph node metastasis." (PMID 38711020, 2024). "The results showed that positive membranous GSDMB expression was more common in cases with lower TNM stage and without lymph node metastasis." (PMID 38711020, 2024).
myasthenia gravis (1 paper, 2021). Myasthenia gravis (MG) is a rare, clinically heterogeneous, autoimmune disorder of the neuromuscular junction characterized by fatigable weakness of voluntary muscles. "We identified several genes that were specifically linked to early onset myasthenia gravis including TNIP1, ORMDL3, GSDMB, and TRAF3." (PMID 34279044, 2021).
Oral ulcer (1 paper, 2022). Erosion of the mucous mebrane of the mouth with local excavation of the surface, resulting from the sloughing of inflammatory necrotic tissue. "Among them, the expression of inflammation-related genes such as CCRL2, HLA-C, GSDMB, HLA-DPB1, and MAPT increased in patients with oral ulcers." (PMID 35958581, 2022).
ovarian serous cystadenocarcinoma (1 paper, 2023). A malignant serous cystic epithelial neoplasm arising from the ovary. "TNFSF14 is positively correlated with GSDMB in KIRC (rho = 0.459, p < 0.0001), SKCM (rho = 0.307, p < 0.0001), and ovarian serous cystadenocarcinoma (OV) (rho = 0.251, p < 0.0001) patients." (PMID 37064151, 2023).
prostate adenocarcinoma (1 paper, 2023). "Log-rank analysis showed that GSDMB gene expression in KIRC had the highest impact on OS (p < 0.0001) and, to a less extent, in prostate adenocarcinoma (PRAD) (p < 0.05)." (PMID 37064151, 2023).
psoriasis vulgaris (1 paper, 2023). Plaque psoriasis is the most common presentation of psoriasis. "The expression level of GSDMB in psoriasis vulgaris lesion tissue is lower than that of normal skin tissue." (PMID 36607980, 2023). "The level of GSDMB protein in the skin lesions of patients with psoriasis vulgaris was lower than that in normal skin tissues (P < 0.05)." (PMID 36607980, 2023). "The study of GSDMB in the pathogenesis of psoriasis vulgaris remains to be further explored." (PMID 36607980, 2023).
renal cell carcinoma (1 paper, 2023). "Despite the association of gasdermin B (GSDMB) with the tumorigenesis of various cancers, whether GSDMB functions as a prognostic biomarker in renal cell carcinoma remains poorly understood." (PMID 37064151, 2023).
squamous cell carcinoma (1 paper, 2023). A carcinoma arising from squamous epithelial cells. "The GSDMB-rs2305480 was a protective variant for adenocarcinoma, but not for squamous cell carcinoma, which could be explained by the different pathogenesis between the two pathological types of NSCLC." (PMID 37359371, 2023).
steatosis (1 paper, 2025). Increased lipid within the cytoplasm of cells. "Gasdermin B has been linked to the transformation of steatosis to steatohepatitis by controlling interleukin‐1β release, but so far no expression studies and mechanisms have been investigated." (PMID 40229590, 2025).
systemic lupus erythematosus (1 paper, 2017). An autoimmune multi-organ disease typically associated with vasculopathy and autoantibody production. "This study aimed to assess the association between 14 single nucleotide polymorphisms (SNPs) in six genes (IRF8, TMEM39A, IKZF3, ORMDL3, GSDMB, and ZPBP2) and systemic lupus erythematosus (SLE) in a Chinese Han population sample." (PMID 28427360, 2017).
Yersinia infections (1 paper, 2024). "Yersinia infections in macrophages trigger caspase-8 cleavage of GSDMD, which in turn initiates pyroptosis, and granzyme A, a lymphocyte-derived enzyme, cleaves GSDMB, which in turn triggers pyroptosis in a number of cancer cell types." (PMID 39655049, 2024).
tumor (163 papers, 2014 to 2026). "We further explored the association of GSDMB expression in different subcellular localizations with tumor progression, TIM, systemic inflammation, chemotherapeutic efficacy and overall survival." (PMID 38711020, 2024). "Here the authors show that mRNA lipid nanoparticles encoding the N-terminal domain of gasdermin B trigger pyroptosis and promote anti-tumor immune responses in preclinical cancer models." (PMID 37454146, 2023). "To assess the relevance of GSDMB for clinical prognosis, we analyzed the association between GSDMB expression and overall survival (OS), cancer stage, and tumor grade across different human cancers." (PMID 37064151, 2023). "Our results indicated that GSDMB expression is associated with tumor immunity and clinical survival prognosis." (PMID 37064151, 2023). "GSDMA expression was highly positively associated with the sensitivity of tumor cells to dexrazoxane, while GSDMB expression showed a markedly positive association with sensitivity to nelarabine, fluphenazine, and perifosine." (PMID 36003332, 2022). "Correlation analysis showed that the mRNA expression of GSDMB was associated with immune infiltrates and the purity of the tumor." (PMID 34957313, 2021). "As a result, the rs8067378 polymorphism increased GSDMB expression, which was significantly associated with tumor development and dissemination in CSCC patients." (PMID 33634141, 2021). "GSDMB over-expression has been described in gastric and cervical tumors compared with normal tissue and this alteration is associated to tumor progression." (PMID 24675552, 2014). "In summary, the expression of GSDMB is associated with low tumor invasiveness." (PMID 38711020, 2024). "Similarly, Granzyme A cleaves GSDMB to promote tumour cell death in tumour cells with high expression of GSDMB, which has been shown to be highly expressed in cancer and associated with tumour metastasis." (PMID 38652105, 2024). "Gasdermin B protein is abundantly expressed in epithelial cells of the alimentary tract and highly susceptible to pyroptosis induced by granzyme A. This mechanism is essential for the elimination of gastrointestinal tumor cells." (PMID 36769513, 2023). "In addition, the association between the high or low expression of GSDMB in normal and tumor tissues and prognosis was also controversial." (PMID 35847844, 2022). "Additionally, it has been demonstrated that the lymphocyte-derived granzyme A (GZMA) hydrolyzes GSDMB at Lys229/Lys244 site to cause tumor cell pyroptosis in the same year." (PMID 36119049, 2022). "Most precancerous samples show moderate GSDMB expression, and most cancer samples show high-level of GSDMB, which overexpression may associate with tumor invasion." (PMID 31501419, 2019). "GSDMB over-expression in these tumours was significantly associated with poor outcome: shorter disease free survival (DSF) and distant metastasis-free survival (DMFS) in the Ur-Rehman dataset (p < 0.001); as well as overall survival (OS) in the TCGA dataset (p < 0.01)." (PMID 27462779, 2016). "There are also evidences that GSDMB presents different splicing variants that may have differential effects on tumor growth and development." (PMID 24675552, 2014). "Recently, Shao and colleagues indicated that cytotoxic lymphocytes, such as cytotoxic T cells (CTLs) and natural killer (NK) cells, can cause tumor cell death through GSDMB‐dependent pyroptosis, suggesting that GSDMB might be a good target to increase effectiveness of cancer immunotherapy." (PMID 33033617, 2020). "The enhanced secretion of GZMA by CTLs is expected to drive tumor-specific pyroptosis via GSDMB cleavage, further amplifying antitumor immunity in a self-reinforcing manner." (PMID 41576171, 2026). "Inducing GSDMB-mediated pyroptosis requires efficient cytosolic delivery of GZMA to cleave GSDMB, a process often thwarted by the membrane repair mechanisms of tumor cells." (PMID 41576171, 2026).
tumor (continued). "This process promoted T-cell activation and infiltration through a positive feedback loop involving IFN-γ-driven upregulation of GSDMB and tumor lysis." (PMID 41291696, 2025). "TNF-α and IFN-γ enhance GSDMB expression, sensitizing tumor cells to killer lymphocyte–mediated cytotoxicity, while IRF2 transcriptionally upregulates GSDMD for pyroptosis." (PMID 40200299, 2025). "GZMA-mediated activation of GSDMB induces extensive pyroptosis in target cells, potentially bolstering anti-tumour immunity." (PMID 39901202, 2025). "Specifically, IBI315 activates the cleavage of GSDMB, leading to the release of inflammatory factors such as IL-18 from tumor cells." (PMID 40452932, 2025). "GSDMB expression, induced by tumor-infiltrating CD8+ T lymphocytes and immune cell-released cytokines like TNF-α and IFN-γ, establishes a positive feedback loop." (PMID 41291696, 2025). "For example, GZMA secreted by cytotoxic T cells has been shown to cleave GSDMB, enabling pore formation in the plasma membrane and triggering pyroptotic death in GSDMB-positive tumor cells." (PMID 41462952, 2025). "These factors further activate T cells, and the activation of T cells, in turn, enhances GSDMB expression through a positive feedback mechanism, forming a tumor cell killing loop." (PMID 40452932, 2025). "Opposing its pro‐tumor functions, GSDMB can exhibit pyroptotic activity and an anti‐tumor effect in the context of an activated anti‐tumor immune response, where its activation, mediated by GZMA from cytotoxic lymphocytes, promotes tumor clearance." (PMID 40783818, 2025). "In summary, GSDMB plays a pivotal role in the initiation and progression of both tumor and non-tumor diseases." (PMID 40452932, 2025). "Tumor cells undergo pyroptosis mediated by gasdermin B (GSDMB), which is triggered by IBI315 and results in T-cell recruitment and activation." (PMID 39338286, 2024). "Research findings demonstrated that GZMA released by CD8+TILs can effectively cleave GSDMB within tumor epithelial cells, culminating pyroptosis." (PMID 39030523, 2024). "In the CT26 model treated with PD-1, the K229A/K244A double mutants at the GSDMB loci resulted in the most pronounced increases in both tumor volume and weight." (PMID 39030523, 2024). "Oltra and co-authors demonstrated that GSDMB-mediated pyroptosis is detrimental to GSDMB cleavage, uncleaved of which promotes pro-tumor effects." (PMID 38695942, 2024). "Patients with positive membranous or nuclear GSDMB expression had more abundant S100A8+ immune cells in the tumor invasive front." (PMID 38711020, 2024). "Our results reveal that CD8+TIL co-expressing GZMA and IFN-γ are crucial in shaping the immune microenvironment, particularly affecting tumor cells that express GSDMB." (PMID 39030523, 2024). "The expression of GSDMB was significantly and positively correlated with the tumor purity of LIHC as well as the degree of infiltration of CD8+ T cells and macrophages." (PMID 38434972, 2024). "In our study, GSDMB expression was evaluated by IHC, which revealed a detailed staining pattern for identifying GSDMB expression in tumor and stromal cells, as well as to determine GSDMB expression in the tumor cell membrane, cytoplasm, and nucleus." (PMID 38711020, 2024). "We found that the expression of GSDMs was significantly higher with higher tumor stage, which was particularly evident in GSDMB, GSDMD, and DFNB59." (PMID 38434972, 2024). "CD8+T cells secreting granzyme A (GZMA) can induce pyroptosis in tumor cells by effectively cleaving gasdermin B (GSDMB), which is stimulated by interferon-γ (IFN-γ)." (PMID 39030523, 2024). "Comparative analysis between CRC and normal colorectal tissues revealed a marked increase in GZMA within TILs, along with a similar upregulation of GSDMB in tumor cells." (PMID 39030523, 2024). "Granzyme A, which is produced by killer lymphocytes, cleaves gasdermin B (GSDMB) and induces pyroptosis in tumor cells, leading to antitumor immune responses." (PMID 39132499, 2024).
tumor (continued). "Intriguingly, GSDMB isoforms 1–3 have been found to be the most abundant isoforms among several tumour cell lines and isoforms 3 and 4 are often up‐regulated in tumours." (PMID 38982510, 2024). "In patients with high GSDMB expression, the inhibitory effects on tumor are not only the direct killing of tumor by chemotherapy drugs, but also the further killing effect of immune cells on tumor." (PMID 38711020, 2024). "Researches have indicated that GZMA can specifically cleave GSDMB at the Lys244 or Lys229 residues in tumor epithelial cells, thereby inducing pyroptosis." (PMID 39030523, 2024). "GSDMB is expressed in humans but not in mice, with five reported subtypes: GSDMB3 and GSDMB4 can induce pyroptosis in tumor cells, while GSDMB1, GSDMB2, and GSDMB5 inhibit the cytotoxic effects of GSDMB3 and GSDMB4." (PMID 39595526, 2024). "GSDMB is tissue-specific and highly expressed in epithelial-derived tumor cells of the digestive system." (PMID 37302999, 2023). "A notable decrease was obtained that tumor CD57+ cells barely expressed GSDMB (0.08%), as compared to the control groups (0.62%)." (PMID 37620327, 2023). "The activated T cells secret IFNγ, enhancing GSDMB expression and establishing a positive feedback loop of T cell activation and tumor cell killing." (PMID 37587833, 2023). "Results showed that the expression of GSDMB has a significant positive relationship with the disease stage of KIRC tumor patients (p < 0.0001)." (PMID 37064151, 2023). "In clinical tumor samples, GSDMB was prevalently expressed in colon, rectal, pancreatic, and cervical cancers." (PMID 37664463, 2023). "Subsequently, we sought to investigate what cleaves GSDMB in tumor cells in the presence of T cells." (PMID 37587833, 2023). "We next analyzed tumor‐infiltrated immune cells and found that knockdown of GSDMB reduced CD3+ and CD8+ T cell infiltration in tumors induced by IBI315." (PMID 37587833, 2023). "Paradoxically, GSDMB can also have an anti-tumour role if its pore-forming pyroptotic function is activated in cancer cells." (PMID 36899106, 2023). "Further investigation is required to clarify if GSDMB-mediated pyroptosis activates anti-tumor immunity and how tumors evade this CAP." (PMID 36742298, 2023). "When we knocked down GSDMB in tumor cells, we found that pyroptosis was reduced and the IL‐18 cytokines in the supernatant decreased." (PMID 37587833, 2023). "A significance decrease was obtained that tumor CD57+ cells barely expressed GSDMB (0.08%), as compared to the control groups (0.62%)." (PMID 37620327, 2023). "Once inside, Granzyme A specifically and effectively cuts the GSDMB protein, leading to the death of the tumor cells through a process known as pyroptosis." (PMID 37077542, 2023). "Critically, Granzyme A was able to cleave GSDMB in vivo with enhanced tumour clearance, highlighting the likely reason many cancers downregulate GSDMB in an oncogenic fashion." (PMID 37266429, 2023). "We found that the potent antitumor effect of IBI315 was dependent on the pyroptosis of tumor cells mediated by activation of gasdermin B (GSDMB)." (PMID 37587833, 2023). "GSDMB is expressed in diverse organs (mostly in gastrointestinal tract, respiratory system, lymphoid tissues) and in multiple tumor types (including breast, gastric and bladder, among others)." (PMID 36899106, 2023). "The tumor inhibition rate of IBI315 on N87 was 116.8%, while the tumor inhibition effect of IBI315 was almost completely blocked after GSDMB was knocked down." (PMID 37587833, 2023). "Meanwhile, the IFNγ secreted by activated T cells leads to an increase in GSDMB as well as PD‐L1 expression on tumor cells." (PMID 37587833, 2023). "Although both GSDMB and GSDME can be activated by killer cells, it seems that GSDME is a more potent tumor suppressor than GSDMB, probably due to the initiation and amplification of GSDME pyroptosis by Caspase-3 in tumors." (PMID 36742298, 2023).